CD4 (CD4 molecule)
Diseases named in the same sentence as CD4 in open-access papers (continued):
Sharing a sentence is not in itself a finding about the gene and the disease.
infection (continued). "For HIV, Doitsh et. al. recently demonstrated in human lymphoid aggregate culture (HLAC) that when HIV enters quiescent CD4+ T cells but does not productively infect them (termed abortive infection), those CD4+ T cells undergo inflammasome activation and pyroptosis." (PMID 24788318, 2014). "However, we did not observe any enhanced inflammation upon infection of CD4-TGFβRIIDN animals with M. tuberculosis." (PMID 24711459, 2014). "It is known that CD4+ T cells producing IFN-γ cells are the major mediators of inflammatory response to infection by T. gondii, although in the absence of CCR5, the accumulation of CD3+CD4+ T cells did not seem to be enough to constrain parasite replication in the gut." (PMID 25119429, 2014). "Next, we infected CD3/CD28 stimulated CD4+ T-cells with wt JR-CSF, S142N or the K421D Env pseudotyped virus, and assessed the infection of the indicated CD4+ T-cell subsets via intracellular p24 staining and multiparametric FACS analysis three days post-infection." (PMID 24957778, 2014). "Therefore, the significantly higher production of IL-6 on day 5 might contribute to the significantly higher recruitment of CD4+ and CD8+ T cells in the control mice at day 9 after H9N2 infection." (PMID 24465940, 2014). "Furthermore, the absence of CD28 impairs development of memory CD4+ T cell responses resulting in failure to clear adult N. brasiliensis worms during secondary infection." (PMID 24516382, 2014). "This is likely because CD4+ T cells are not essential for clearance of primary HKx31 infection." (PMID 25347065, 2014). "Interestingly, upon re-infection, there was no enhancement of the CD4+ cytokine response in any subject." (PMID 25397604, 2014). "Similarly, praziquantel efficacy – as measured by parasitological cure rates and the reduction in intensity of the infection – was not influenced by the level of CD4+ cell counts." (PMID 25671125, 2014). "CD8+ and CD4+ T cells kill infected hepatocytes through diverse mechanisms and induce sterile protection (i.e., no blood stage infection) in mouse models." (PMID 25452745, 2014). "In contrast to CD14+ DCs, infection of CD1c+ DCs and LCs did not impair their capacity to induce allogeneic CD4+ T cell proliferation, showing that DENV-mediated inhibition of T cell proliferation was DC subset specific and not a direct generic effect of the virus either on DCs or T cells." (PMID 25474532, 2014). "Recently, and in contrast to what previously observed in dividing cells, it has been reported that, in resting CD4+ T cells, naïve or memory, and independent of their infection status, Cyclin T1 and T-loop-phosphorylated CDK9, are expressed at low levels and increase upon activation." (PMID 24736215, 2014). "Combination antiretroviral therapy (cART), whether started during the primary infection or in the chronic phase of HIV-1 infection, generally leads to a biphasic increase in CD4 T cell counts, with a rapid increase during the first months, followed by a more gradual rise." (PMID 24465584, 2014). "A PRRSv specific proliferation of CD4+ T cells would likely not occur as early as 2 dpi, but a bystander proliferation of CD4+CD8+ memory cells may be a non-specific effect of PRRSv infection, and therefore cannot be excluded." (PMID 25497114, 2014). "Its CSF concentration exceeded age-adjusted norms in all HAD patients, 75% of NA CD4<50, 40% of NA CD4 50–199, and 42% of primary infection, indicating common neuronal injury with untreated systemic HIV disease progression as well as transiently during early infection." (PMID 25541953, 2014). "Instead, under circumstances where infection will ultimately result in lytic cell death regardless of T-cell killing, pathogen containment and clearance is dependent on the production of cytokines by effector CD4+ and CD8+ T cells." (PMID 25121482, 2014).
infection (continued). "The relative contribution of CD4 and CD8 T cells in providing protective immunity in the reproductive tract can vary based on the nature of the invading pathogens; however, new studies indicate that CD4 and CD8 TRM can provide early in situ immune responses to infection of the FRT." (PMID 25071787, 2014). "Moreover, the increased production of RANTES on day 5, which is chemotactic for T cells, might contribute to higher infiltration of CD4+ and CD8+ T cells in the control mice at day 9 after H9N2 infection." (PMID 24465940, 2014). "This was paralleled by an increase in the percentage of CD4 T cells with an effector memory phenotype (CD62L− CD45RA−, P<0.05), while the frequencies of terminal effector (CD62L− CD45RA+) and central memory (CD62L+ CD45RA−) CD4 T cells remained roughly constant throughout infection." (PMID 24763747, 2014). "Treatment of filarial infection and consequent cure resulted in significantly decreased frequencies of CD4+ T cells expressing IL-10, IL-19, IL-24 and IL-26 after parasite-antigen stimulation whereas those who continued to harbor infection did not exhibit reduction in these frequencies." (PMID 24699268, 2014). "Thus, partial depletion of CD4+ T-cells prior to infection did not result in a more benign course of infection and was sufficient to generate the higher viremia phenotype." (PMID 25356757, 2014). "Protection from infection was dependent on CD4+ T-cells, but appeared independent of Foxp3+ Tregs." (PMID 24098124, 2013). "The presence of high viral load has an impact on several mRNA transcripts, however, the effect of other factors such as CD4 count and nadir CD4 has a significant negative correlation for IL8; this is consistent with data in the literature that associates infection with elevated IL8." (PMID 23721325, 2013). "Similarly, the vast majority of effector CD4+ T-bet+ cells from WT mice failed to express KLRG-1 on days 11 or 14 infection." (PMID 23593003, 2013). "On the other hand, we have shown that allogeneic co-culture of mDC and CD4+ T lymphocytes induced higher levels of CD69 and CD25 expression and proliferation, independently of the presence of HIV-1, and that it resulted in higher viral trans-infection and replication in CD4+ T cells." (PMID 23590845, 2013). "However, HIV does not efficiently establish infection in resting memory CD4+ T cells, and activated CD4+ T cells typically die within days after infection." (PMID 23874178, 2013). "However, a recent report demonstrated that resting CD4+ T cells are capable of producing Gag protein without spreading infection in an in vitro latency model, suggesting another level of HIV latency regulation." (PMID 23587031, 2013). "Rather than resistance of CD4 T-cells to infection, a reduced immune response and lower number of target cells generated for productive infection during PHI may play an important part in LTNP/EC status." (PMID 23630526, 2013). "Indeed, early studies supporting efficient HIV-1 trans infection by immature DC were not confirmed, as mature DC appear more effective at trans infection of CD4+ T cells." (PMID 24278768, 2013). "Different CD4+ T cell subsets, in particular the resting central and transitional memory subsets known to harbor the latent HIV-1 reservoir during ART, could be involved in HIV-1 trans infection." (PMID 24278768, 2013). "Modulation of CD4+ T cell and innate APC function during pre-patent schistosome infection may represent one aspect of the exploitation of these cell populations by schistosomes during the establishment of infection." (PMID 23556020, 2013). "Besides direct infection of DCs, the majority of HIV-1 virions are captured by DCs and transported to lymphoid tissues where upon transformation to mature DCs the virus is transferred to CD4+ T lymphocytes." (PMID 23741304, 2013).
infection (continued). "Importantly, at the infection site, in the absence of Tfh cells, we found that ICOS deficiency actually led to an increased percentage of CD4+ T cells producing IL-4 and IL-13 protein." (PMID 23319295, 2013). "The IL-27R, WSX-1, is required to limit IFN-γ production by effector CD4+ T cells in a number of different inflammatory conditions but the molecular basis of WSX-1-mediated regulation of Th1 responses in vivo during infection has not been investigated in detail." (PMID 23593003, 2013). "Importantly, host-derived CD40L within virions results in increased virus attachment to B cells and more efficient B cell mediated trans infection of autologous CD4+ T cells compared to virions without CD40L." (PMID 24278768, 2013). "Thus, in both scenarios the memory CD4 T cell response characteristics were dictated by the challenge infection rather than imprinted by priming." (PMID 23762323, 2013). "In addition, a significantly higher proportion of infiltrating T-cells were CD8+ CTL, rather than CD4+ cells, following vΔK7 infection compared with vK7 or vK7-rev." (PMID 23580427, 2013). "Infection with H. polygyrus did not change the percentage of MLN CD4+Foxp3+ Treg cells in either WT or ICOS−/− mice, indicating that ICOS deficiency impaired the expansion of CD4+Foxp3+ Treg cells and CD4+Foxp3− Teff cells to a similar extent." (PMID 23319295, 2013). "On the contrary, WSX-1−/− mice generate more IFNγ-producing CD4+ T cells than wild-type mice after infection with Toxoplasma gondii, indicating that IL-27 signal is not necessary for the generation of Th1 immunity to the infection." (PMID 24068935, 2013). "CD8 CTL specific for HIV-1, HSV-2, and EBV HLA-B*27 and HLA-B*57 restricted epitopes were resistant to Treg cell-mediated suppression, explaining how such cells continue to proliferate and control infection(s) in LTNP, which might also apply to the virus-specific CD4 T cells." (PMID 23459797, 2013). "Whereas reduced memory in mice lacking CD4 T cell appears only several weeks after infection, CD4 T cells have been found to be critical during the initial priming process, during which they render CD8 T cells with enormous potential to proliferate upon reencounter with the pathogen months later." (PMID 24171157, 2013). "Thus, it does not appear that intrahepatic CD4+ T cells significantly contribute to production of the dominant tissue-chemotaxin(s) in WSX-1−/− mice during infection." (PMID 24244314, 2013). "Indeed, in contrast to Itgb8 (CD11c-Cre) mice, no enhancement of CD4+ T-cell IL-13 production was observed early during infection in Foxp3+ Treg-depleted mice." (PMID 24098124, 2013). "However, CD4 count often will not increase as rapidly as it generally occurs with successful therapy of HIV-1 mono-infection." (PMID 23824279, 2013). "Thus, to determine the importance of this pathway in promoting TGFβ signalling in CD4+ T-cells during T. muris infection, we analysed T-cell responses in C57BL/6 control mice and mice lacking integrin αvβ8 on DCs (Itgb8 (CD11c-Cre) mice) during infection." (PMID 24098124, 2013). "Since KR13 appears to induce gp41 6-helix bundle formation, and the latter is a required step in cell entry, we evaluated whether KR13 might enhance infection of CD4 negative cells." (PMID 24330857, 2013). "Taken together, these results indicate that protection from infection in the absence of integrin αvβ8 expression on DCs is not via a direct effect of innate lymphoid cells, but driven by a classical CD4+ T-cell response, although a role for innate cells in initial priming cannot be ruled out." (PMID 24098124, 2013). "Therefore, during chronic LCMV-DOC infection, the inhibition of virus-induced Treg cell expansion is a distinct function of IL-21, which is not accompanied by elevated IL-17 production of CD4+ T cells." (PMID 23696736, 2013).
infection (continued). "While CD8+ T cells have redundant function with CD4+ T cells, such as activating infected macrophages with IFN-γ, as well as the use of the granule exocytosis pathway, CD8+ T cells also have the potential to play a unique role in the recognition and containment of intracellular infection with Mtb." (PMID 23805289, 2013). "By contrast, the pathways by which IL-27 inhibits effector T cell accumulation in non-lymphoid tissues during infection are poorly understood, but may include limiting CD4+ T cell proliferation or enhancing cellular apoptosis in situ." (PMID 24244314, 2013). "Thus, if diagnosis occurs in late stage infection and no other clinical data is available, e.g. CD4 counts, the problem with false recent classification becomes more severe." (PMID 23613753, 2013). "Reduced plasma levels of IL-21 have been found in HIV-infected individuals, and we recently showed that pathogenic SIV-infection of RMs, but not nonpathogenic SIV infection of sooty mangabeys is associated with a significant loss of IL-21-producing CD4+ T cells." (PMID 23853592, 2013). "This indicated that while expression of the human CD4, CCR5 and cyclin T1 transgenes enabled the hCD4/R5/cT1 mouse CD4+ T cells and myeloid-lineage cells to be infected with HIV-1, hCD4/R5/cT1 mouse myeloid-lineage cells supported infection more robustly than the CD4+ T cells." (PMID 23691059, 2013). "The seroconversion of incident infection in this cluster was determined over 467 days as the time between the last HIV-negative and the first HIV-positive test, which might partially explain the CD4 decline to 311 in this subject." (PMID 24349005, 2013). "However, if the initial infection is not controlled and chronic infection is established, CD4+ T cells become more important for long-term control of infection." (PMID 23508691, 2013). "However, Cxcr3−/− mice receiving Cd40l−/− CD4+ T cells survived the infection, indicating that CD40L does not mediate CXCR3+CD4+-dependent protection." (PMID 24130498, 2013). "On the other hand, in NR6, CD8+ T cells might have mainly worked for protection since IFN-γ-producing CD8+ T cells but not CD4+ T cells against NRT1 were detected without an increase in NI activity after infection." (PMID 24376571, 2013). "Accordingly, the FIV–CD134 interaction may influence profoundly the development of antigen-specific immune responses as FIV will target preferentially the very cells that have been triggered to expand in response to infection, just as HIV infects HIV-specific CD4+ T cells preferentially." (PMID 23992667, 2013). "In the absence of PMNs, at 8 days of infection, there is an increase in the proportion of other leukocytes such as CD4+ and CD8+ T cells with up-regulated expression of the effector/memory-like activation surface marker glycoprotein CD44 in Brucella infected mice." (PMID 23458832, 2013). "This could explain why addition of E2 before and after infection did not have the same effect as pre-treatment alone in CD4+ T-cells." (PMID 23614015, 2013). "However, after inoculation of primary human blood cells such as CD4 T cells, macrophages or dendritic cells, infection rates were very low, and a spreading infection was never established." (PMID 24058563, 2013). "Furthermore, no immunopathology was apparent in Il21−/− mice over the course of the infection, nor was there a defect in development of IL-10+ CD4+ T cells in chronically infected Il-21−/− mice." (PMID 23667536, 2013). "In the absence of E2, CD4+ T-cells from women had lower levels of infection than that found in men." (PMID 23614015, 2013). "CD4+ T-cells play a key role in the resolution of T. spiralis infection, so to assess if CD4+ T-cells could restore I-cell hyperplasia and hypophagia in SCID mice, CD4+ T-cells (>90% purity), were adoptively transferred into SCID recipients before infection." (PMID 23349631, 2013). "Thus, HIV-1 cis infection of DC is enhanced by coculture with CD4+ T or B lymphocytes but not with CD8+ T cells." (PMID 24278768, 2013).
infection (continued). "In this condition, transfer of CD4+ T cells failed to rescue PtprcL3X mice from lethal infection." (PMID 24068938, 2013). "Since the cytokine levels were elevated before the T cell response was initiated, these data suggest that antigen-specific CD4 T cells may not be the primary source of serum IFNγ during infection." (PMID 23754944, 2013). "Here we show that at early stages of Brucella infection a heterogeneous effector T cell population including CD8+ CTLs and CD4+CTLs both expressing high levels of Granzyme B is present in the spleen and LNs, whereas CD4+Granzyme B- IFN-γ+ T cells develop at later stages of the infection." (PMID 24367519, 2013). "Thus, there was a strong negative correlation between the amount of TNF-α+IL-2+ CD4 T cells induced by the vaccines and the level of bacteria in the lungs 6 weeks after infection (R2 = 0.93 and 0.75, and p<0.0001 for Ag85B and TB10.4, respectively)." (PMID 23977248, 2013). "Further, CD4 T cells are also essential for the control of HSV-2 replication at the site of infection, i.e., the vaginal tract, and in HSV-1 infection CD4 T cells are thought to be the major mediator of immunity in the cornea, but simultaneously may also be a major inducer of immunopathology." (PMID 23717308, 2013). "IFN-γ secretions from overnight IFN-γ-assays ensures that the responses are from in vivo sensitized CD4+ T cells to these epitopes via natural infection and/or vaccinations, i.e. memory CD4+ T cells rather than by naïve CD4+ T cells expanded in vitro in response to the in vitro presented epitopes." (PMID 23641949, 2013). "Interestingly, direct infection of non-activated primary CD4+ T cells by free HIV-1 was almost null, even under α-CD3 (mAb OKT3) or SEA activation conditions." (PMID 23590845, 2013). "We can speculate that the efficiency of this process will depend in part on the integrity of functional activity of the APC and CD4+ T cells, that is, their expression of receptors and intracellular and cell-cell pathways known to be involved in both HIV-1 cis and trans infections." (PMID 24278768, 2013). "However, under supraphysiological conditions of infection, this linkage is not absolute; and the defective virus retains some capacity to systemically reduce CD4+ T cells." (PMID 22640559, 2012). "The approach of using the BED-CEIA assay and CD4<200 cells/μl and VL<400 copies/mL as surrogate markers for FPR may facilitate the identification of recent infections in situ using the HIV monitoring tools already available or being scaled up in many low income countries." (PMID 22363755, 2012). "Furthermore, while the number of CD4+Foxp3− T cells was similar between the groups on day 8 post infection (data not depicted), CD8+ effector T cells were elevated in the lungs of IL-10−/− mice." (PMID 22393401, 2012). "Recent studies using a model of simian immunodeficiency virus (SIV)-infection and in situ visualization techniques demonstrated that SIV-specific CD8+ T-cells (effectors) are recruited into the vaginal mucosa and lymph nodes in close proximity to SIV-infected CD4+ T-cells (targets)." (PMID 22470433, 2012). "Using simultaneous in situ hybridization and immunophenotyping techniques, HIV-1 expressing CD4+ T lymphocytes, macrophages, and dendritic cells are detected at the intraepithelial layer within 3 days of infection, as observed in SIV/macaque system at early stages of infection." (PMID 22412886, 2012). "Indeed, we observed a statistically significant negative correlation between RC and average CD4 counts for the first year post infection, suggesting a role for RC in defining this important parameter of pathogenesis at early stages after infection." (PMID 23209412, 2012).